PBK (PDZ binding kinase)
Diseases named in the same sentence as PBK in open-access papers (continued):
Sharing a sentence is not in itself a finding about the gene and the disease.
breast carcinoma (continued). "PBK/TOPK targets Thr450 of LGN/GPSM2 during mitosis, suggesting that the PBK/TOPK-LGN/GPSM2 pathway could be a potential target for breast cancer therapies." (PMID 41362722, 2026). "Additionally, PBK/TOPK mediates geranylgeranylation signaling to promote breast cancer cell proliferation." (PMID 41362722, 2026). "According to our analysis, the overexpression of PBK/TOPK in luminal A was significantly lower than that of HER-2(+) and TNBC types, which once again confirmed that PBK/TOPK overexpression is associated with a worse prognosis for breast cancer." (PMID 36171591, 2022). "This experiment confirmed the overexpression of PBK/TOPK in breast cancer tissues." (PMID 36171591, 2022). "Breast cancer patients with high expression of PBK/TOPK have a poor prognosis." (PMID 36171591, 2022). "The results suggest that the expression level of PBK is related to the prognosis of breast cancer." (PMID 36171591, 2022). "Therefore, the objective of the present study was to study the relationship between PBK/TOPK expression and clinicopathological indicators as well as the survival of patients with breast cancer." (PMID 36171591, 2022). "As the prognosis of stage 3 breast cancer patients was worse than those of patients in stages 1 and 2, the high expression of PBK/TOPK indicated that it was associated with the proliferation of malignant tumors and tumor progression, which was consistent with the existing evidence." (PMID 36171591, 2022). "PBK/TOPK is highly expressed in several types of cancer including lung adenocarcinoma, ovarian cancer, gastric carcinoma, breast cancer, nasopharyngeal carcinoma, and colon cancer." (PMID 33842463, 2021). "PBK is likely to play a crucial role in cell division and cytokinesis in breast cancer, but this gene might be liable for cell division and cytokinesis in pituitary prolactinoma." (PMID 33709028, 2021). "Notably, higher PBK/TOPK mRNA expression was found in 9 datasets, and lower PBK/TOPK mRNA expression was found in 1 dataset of breast cancer." (PMID 34603451, 2021). "Moreover, reduction of PBK/TOPK expression decreased tumor growth and survival in high-grade malignant lymphomas, as well as in breast cancer cells." (PMID 33670114, 2021). "To determine whether PBK mediates the geranylgeranylation signaling in breast cancer cell proliferation, we examined the effect of PBK knockdown and the kinase inhibition on MDA-MB-231 cell proliferation." (PMID 25745361, 2015). "Finally, three antibodies (PDZK1, ANLN, PBK) were successfully optimised on full-face paraffin embedded sections of breast cancer tissues and subsequently selected for screening on TMAs." (PMID 23547718, 2013). "In addition, PBK is a shared down-regulated genes with the highest connectivity degrees in the Narciclasine and Bruceine D treatment groups, indicating that it played important role in breast cancer cell proliferation." (PMID 38215156, 2024). "In addition, PBK/TOPK may promote the proliferation of breast cancer cells by mediating the geranyl-geranylation signaling pathway." (PMID 36171591, 2022). "Therefore, one of our research plans in the future is to study the difference in clinical impact between breast cancer in which PBK/TOPK is mainly expressed in the nucleus of cancer cells and that in which it is mainly expressed in the cytoplasm of the cancer cells." (PMID 36171591, 2022). "Furthermore, our studies have shown that PBK is connected to geranylgeranylation signaling most likely in advanced stage breast cancer, and essential for breast cancer cell proliferation, confirming that PBK is an important molecular target for breast cancer therapy." (PMID 25745361, 2015). "In breast cancer cell lines, the CDK/cyclin B1 complex can increase the phosphorylation level of PBK by inhibiting protein phosphatase alpha-1, thereby promoting mitosis." (PMID 39649886, 2024). "For patients with stages 1–2 breast cancer, the expression level of PBK/TOPK was negatively correlated with OS." (PMID 36171591, 2022).
breast carcinoma (continued). "The expression level of PBK/TOPK was negatively correlated with both the OS and DFS of breast cancer patients." (PMID 36171591, 2022). "In breast cancer molecular typing, luminal A and luminal B breast cancers have better prognosis than HER-2 positive and TNBC breast cancers, and the expression of PBK/TOPK in HER-2 positive and TNBC is higher than that in luminal A or luminal B types." (PMID 36171591, 2022). "In luminal types of breast cancer, ER and PR hormone receptors are positive, and the expression of PBK/TOPK is relatively low." (PMID 36171591, 2022). "Four hub genes, namely TOP2A (p=0.036), MELK (p=0.021), PBK (p=0.043), and RRM2 (p=0.012), were upregulated during breast cancer progression from normal tissue to DCIS and downregulated during disease progression from DCIS to IDC." (PMID 34094915, 2021). "Meanwhile, we found that CEP55, HIST1H2BO, IFI6, KIAA0101, PBK, SPAG5, and SPP1 were significantly upregulated in breast cancer compared to normal samples." (PMID 34055036, 2021). "PBK/TOPK over-expression contributes to tumor growth and proliferation in breast cancer, colorectal cancer, and Ewing sarcoma." (PMID 27347940, 2016). "PBK/TOPK is highly expressed in various types of malignancies, such as malignant peripheral nerve sheath tumors, leukemia, breast cancer, and lymphoma." (PMID 27347940, 2016). "Antibodies against anillin (ANLN), PDZ-Domain Containing 1 (PDZK1) and PDZ-Binding Kinase (PBK) demonstrated specificity via Western blot analysis and exhibited concordant IHC staining on cell pellet arrays across 7 breast cancer cell lines." (PMID 23547718, 2013). "Among them, PBK and NEK2 were experimentally confirmed to promote tumor cell proliferation, providing novel insights for early diagnosis and therapeutic strategies in breast cancer." (PMID 41727445, 2026). "With regard to the practical implications, this study provides evidence that PBK/TOPK protein is overexpressed in breast cancer tissues and predicts a poor prognosis for patients with breast cancer, which can provide clinicians with diagnosis and treatment value." (PMID 36171591, 2022). "Furthermore, according to our survival analysis, the expression level of PBK/TOPK was negatively correlated with both the OS and the DFS of breast cancer patients." (PMID 36171591, 2022). "In addition, one study suggested GPSM2 was involved in the cell division of breast cancer cells and was regulated by PBK/TOPK." (PMID 32195179, 2020). "Taken together, both immunoblotting and immunofluorescent staining data clearly indicate that geranylgeranylation controls PBK gene expression and PBK protein level in ER- breast cancer MDA-MB-231 cells, but not in ER+ breast cancer MCF7 cells." (PMID 25745361, 2015). "The breast cancer cell must have a signaling context of geranylgeranylation signaling and the Hippo-YAP/TAZ pathway that confers the effect of atorvastatin on down-regulation of PBK." (PMID 25745361, 2015). "Importantly, atorvastatin or the geranylgeranyltransferase I inhibitor GGTI-298 inhibited breast cancer cell proliferation through inactivation of YAP signaling and down-regulation of PBK." (PMID 25745361, 2015). "Consistent with the effect on the cell proliferation, atorvastatin treatment significantly down-regulated the mRNA level of PBK in the ER- breast cancer MDA-MB-231 cells, but not in MCF7 cells." (PMID 25745361, 2015). "Thus, down-regulation and inhibition of PBK by either targeting geranylgeranylation signaling and the Hippo-YAP/TAZ pathway or directly impairing the kinase activity are promising approaches for breast cancer therapy, particularly advanced stage breast cancer therapy." (PMID 25745361, 2015). "In contrast, ER and PR hormone receptors are negative in HER-2 positive and TNBC breast cancer, the expression of PBK/TOPK is higher, and the expression level of PBK/TOPK is negatively correlated with the positive expression of ER and PR." (PMID 36171591, 2022).
breast carcinoma (continued). "However, expression of PBK is responsive to geranylgeranylation signaling only in ER- breast cancer MDA-MB-231 cells, not in ER+ breast cancer MCF7 cells." (PMID 25745361, 2015).
colon carcinoma (34 papers, 2015 to 2026). "In this study, we proposed the association between high PBK/TOPK expression and favorable prognose in patients with colon cancer." (PMID 35203508, 2022). "Similarly, PDZ binding kinase (PBK or TOPK) is a serine–threonine mitogen‐activated protein kinase involved in cytokinesis, and studies have associated it with the growth of colon cancer cells." (PMID 39087856, 2024). "PBK/TOPK-high colon cancers are more likely to have mutations in several DNA damage repair genes." (PMID 35203508, 2022). "Based on large-scale bioinformatics analysis, we discovered that elevated PBK/TOPK expression predicted a favorable outcome in patients with colon cancer and was positively associated with immune infiltration levels of CD8+ T cells, CD4+ T cells, natural killer cells, and M1 macrophages." (PMID 35203508, 2022). "Mutations in DNA repair genes were enriched in PBK/TOPK-high colon cancers." (PMID 35203508, 2022). "In this study, we investigated the prognostic role of PBK/TOPK in colon cancer, with a focus on genes involved in immunity." (PMID 35203508, 2022). "PBK/TOPK co-expressed genes were enriched in the gene set that represents a colon cancer MSI signature." (PMID 35203508, 2022). "We found that colon cancer patients with high PBK/TOPK expression showed higher MSI and TMB, which is associated with neoantigen burden." (PMID 35203508, 2022). "Together with previous findings, our analysis supports that PBK/TOPK expression exhibits a favorable prognosis in patients with colon cancer." (PMID 35203508, 2022). "Here, we investigated the correlation between PBK/TOPK expression and tumor immunity and its prognostic value in colon cancer." (PMID 35203508, 2022). "The OS analysis results also demonstrated a correlation between a good prognosis and PBK/TOPK expression in stage I-III colon cancers." (PMID 35203508, 2022). "Even though PBK/TOPK inhibitor can significantly suppress tumor growth as well as increasing colon cancer cell apoptosis in cell model." (PMID 30286126, 2018). "Treated with HITOPK-032 (an inhibitor for PBK), subcutaneous tumors were strikingly diminished in mice models of colon cancer, glioma and nasopharyngeal carcinoma." (PMID 28525379, 2017). "To further validate PBK’s role in GIC growth and survival, we treated different GIC cultures with a pharmacological inhibitor used previously to target PBK in colon cancer cells." (PMID 26081429, 2015). "Similarly, in colon cancer, PBK expression has been found to correlate with heightened immune cell infiltrates, warranting additional research into PBK as a potential predictive biomarker for immunotherapy response." (PMID 38755218, 2024). "In this study, we conducted a large-scale bioinformatic analysis of the genetic and clinicopathologic data of patients with colon cancer and revealed that PBK/TOPK could act as a favorable prognostic biomarker in colon cancer." (PMID 35203508, 2022). "High PBK/TOPK expression in colon cancer was correlated with an increased infiltration level of cytotoxic immune cells, whereas activated CD8+ T- and NK-cell-infiltrated tumors also exhibited decreased infiltration of Treg cells and M2 macrophages that have immunosuppressive roles in TME." (PMID 35203508, 2022). "Furthermore, the expression of PBK/TOPK was correlated with the expression of T-cell cytotoxicity genes in colon cancer." (PMID 35203508, 2022). "PBK/TOPK expression gradually decreased as colon cancer progressed." (PMID 35203508, 2022). "We next examined whether PBK/TOPK expression can differentiate patients with colon cancer exhibiting a different prognosis status." (PMID 35203508, 2022).
colon carcinoma (continued). "Given the correlation among MSI-H, the mutational load, and cytotoxic immune cell infiltration, upregulation of PBK/TOPK in colon cancer could be a potential candidate marker to guide patient selection for immunotherapy." (PMID 35203508, 2022). "Further studies are required to determine if analyzing the expression level of PBK/TOPK in colon cancer may be a clinically viable method for predicting TMB levels." (PMID 35203508, 2022). "Previous studies have shown that PBK is highly trans-activated in various cancers including ovarian cancer, lymphoma, kidney cancer, and colon cancer, which is a promising molecular target for cancer-targeted therapy." (PMID 36685860, 2022). "The PBK inhibitor HI-TOPK-032 could effectively suppress colon cancer and glioblastoma growth in vitro and in vivo." (PMID 30778048, 2019). "Therefore, PBK/TOPK expression levels could serve as a surrogate biomarker for identifying colon cancer patients with high TMB." (PMID 35203508, 2022). "We found that high PBK/TOPK expression correlates with increased accumulation of antitumor immune cells and favorable prognosis in patients with colon cancer." (PMID 35203508, 2022). "Since colon cancer progresses with a stepwise accumulation of genetic or epigenetic alterations and changes, we assessed PBK/TOPK expression levels in different stages of colon cancer." (PMID 35203508, 2022). "Analysis of TCGA data base revealed that the PBK promoter was hypo-methylated in colon cancer tissues compared with normal tissues, indicating that PBK/TOPK can be epigenetically induced in colon cancers." (PMID 35203508, 2022). "We also examined PBK level and PARP cleavage in miR-770-5p-transfected HCT116 human colon carcinoma cells." (PMID 28333152, 2017). "Given the oncogenic role of PBK/TOPK in the process of tumorigenesis and tumor progression, it is interesting to find that high expression of PBK/TOPK correlates with an improved prognosis in colon cancer." (PMID 35203508, 2022). "Our meta-analysis of survival data further confirmed a positive correlation between PBK/TOPK expression and OS in colon cancers, but not in ovarian cancers." (PMID 35203508, 2022). "PBK/TOPK appears to promote mitosis for cancer cell proliferation according to our pathway analysis data (data not shown) and those of previous reports; however, how much or how independently PBK/TOPK contributes to the proliferation of colon cancer cells is not clear." (PMID 35203508, 2022).
colorectal cancer (34 papers, 2015 to 2026). A primary or metastatic malignant neoplasm that affects the colon or rectum. "The inhibition of PBK/TOPK could benefit those colorectal cancer patients with a KRAS or BRAF mutation and those with metastasis, which represented 30–40% of all cases, and this may represent a new avenue of investigation for targeted therapy." (PMID 33670114, 2021). "PBK further enhances cell proliferation by phosphorylating histone H3 and inhibits colorectal cancer migration and invasion through CDH1 stabilization." (PMID 41362722, 2026). "The radiation-inducible miR-770 boosted apoptosis via direct targeting of PDZ-binding kinase (PBK), which sensitized colorectal cancer (CRC) cells to radiation both in vitro and in vivo." (PMID 32585857, 2020). "PBK/TOPK immunoreactivity was analyzed by immunohistochemistry in 162 cancer specimens from primary colorectal cancer patients." (PMID 30286126, 2018). "In addition, TOPK interacts with PRPK to regulate colorectal cancer metastasis 87, while PBK overexpression promotes HCC metastasis via the ETV4-uPAR pathway." (PMID 41362722, 2026). "Moreover, the inhibitor of PBK can suppress the proliferation of colorectal cancer cells with PBK expression." (PMID 38661103, 2024). "It is also reported that PBK/TOPK knockdown in colorectal carcinoma cell lines increased apoptosis and G2/M arrest in tumor cells, indicating that PBK may be a target for relevant inhibitors to sensitize tumor cells to chemotherapy-induced apoptosis." (PMID 34859049, 2021). "Recent studies have shown that miR-216b mediates the downregulation of PBK-enhanced chemosensitivity of colorectal cancer, and PBK inhibition could sensitize tumors to radiation." (PMID 30778048, 2019). "PBK/TOPK expression might be used as an independent prognostic marker for colorectal cancer patients." (PMID 30286126, 2018). "PBK/TOPK may also accelerate tumorigenesis in colorectal cancer." (PMID 30286126, 2018). "A positive feedback loop between PBK and ERK was identified in the colorectal cancer cell line HCT116, resulting in uncontrolled cell proliferation." (PMID 39649886, 2024). "A series of 1-phenyl phenanthridin-6 (5H)-one derivatives have also been identified as a novel chemical class of PBK/TOPK inhibitors, among which 9g compound displayed superior anticancer activity, even compared to OTS964, against colorectal cancer." (PMID 33670114, 2021). "Background/Objectives: PDZ-binding kinase (PBK) regulates mitosis, but its clinical significance and cellular localization in colorectal cancer (CRC) remain unclear." (PMID 41681955, 2026). "We suggest that PBK/TOPK expression, detected by IHC staining, could be used as an independent prognostic marker for colorectal cancer patients." (PMID 30286126, 2018).